EHMT2 (euchromatic histone lysine methyltransferase 2)
Diseases named in the same sentence as EHMT2 in open-access papers (continued):
Sharing a sentence is not in itself a finding about the gene and the disease.
cancer (continued). "DMAP analysis showed a comparatively higher expression of EHMT2 during CD4+/CD8+ T-cell lineage hematopoietic commitment and supports the hypothesis of a preferential cancer dependency based on hematopoietic lineage commitment." (PMID 35710782, 2022). "G9a, also known as EHMT2 (Euchromatic histone-lysine N-methyltransferase 2) a nuclear lysine histone methyltransferase that mainly catalyzes histone H3 lysine 9 (H3K9), is involved in cancer invasion and metastasis." (PMID 34552922, 2021). "Euchromatic histone lysine methyltransferase 2 (G9a, EHMT2) and suppressor of variegation 3-9 homolog 1 (SUV39H1) predominantly methylate histone H3K9 to induce the formation of heterochromatin, and are overexpressed in several types of cancer." (PMID 30544763, 2018). "The analysis exhibited that PR-specific hubs were associated with statistically significant pathways such as Wnt SP, transcriptional misregulation in cancer, ERCC6 (CSB), and EHMT2 (G9a) positively regulate rRNA expression, and chromatin modifying enzymes involved in tumor formation and development." (PMID 28892521, 2017). "We demonstrated that G9a (also known as euchromatic histone-lysine N-methyltransferase 2, EHMT2) plays an important role in the development of GEM resistance via autocrine and paracrine stimulation of cancer cells and pancreatic stellate cells." (PMID 27531902, 2016). "Although elevated levels of EHMT2 expression have previously been observed in various cancer tissues when compared with normal tissues, the clinical significance of EHMT2 expression in tumors not yet been fully elucidated." (PMID 27174920, 2016). "EZH2, EHMT2, and SMYD3 are vital epigenetic regulators that could be targeted for cancer therapy." (PMID 35300417, 2022). "In addition to the PRC complex, several regulators of histone H3K9 methylation, such as the SET domain-containing histone methyltransferases SETDB1 and G9a (also known as euchromatic histone lysine N-methyltransferase 2, EHMT2), play important roles in regulating pluripotency and cancer stemness." (PMID 35455671, 2022). "The fact that EHMT2 functions in the regulation of various processes, including cellular differentiation, proliferation, epithelial-to-mesenchymal transition (EMT), senescence, DNA replication and DNA repair among others, has suggested a key role for this protein in the epigenetics of human cancers." (PMID 34249932, 2021). "Anti-cancer drugs (HMT inhibitors) have also been developed that target the HMTs EZH2, DOT1-like histone lysine methyltransferase (DOT1L), euchromatic histone lysine methyltransferase 2 (G9A), the histone-lysine N-methyltransferase SUV39H1 and protein arginine methyltransferases (PRMT1/3/45/6/8)." (PMID 33391954, 2021). "Among these, the SET domain-containing histone methyltransferases SUV39H1, SETDB1, and G9a (EHMT2), which play distinct roles in the maintenance of H3K9 methylation states and the organization of heterochromatin, are gaining much attention in recent cancer literature, as reviewed by Saha & Muntean." (PMID 34775469, 2021). "For this reason, in this cancer type, EHMT2 levels may not reflect its actual regulatory activity." (PMID 32292512, 2020). "Moreover, neither EHMT2 knockdown, EHMT2 knockout, nor treatment with UNC0642, A366, or BRD4770 affected cancer cell growth in a clonogenic assay, indicating that the impact of EHMT2 on tumor growth is largely NK cell-driven (cancer cell-extrinsic)." (PMID 41366520, 2026).
tumor (194 papers, 2012 to 2026). "Next, to determine the role of NK cells in mediating the Ehmt2 loss-induced tumor suppression in the EMT6 model, we depleted the NK cells in BALB/c mice using anti-Asialo-GM1 antibody." (PMID 41366520, 2026). "Collectively, these results demonstrate that Ehmt2 loss promotes tumor suppression in the presence of the host immune system." (PMID 41366520, 2026). "A possible oncosuppressor role of DUSP4 has also been identified in head and neck SCC (HNSCC), in which the expression of G9A/EHMT2 histone methyltransferase was found to be associated with tumour growth and poor prognosis." (PMID 40943262, 2025). "TCGA data analysis demonstrated a robust association between EHMT2 expression and pathological features in PCa, with elevated EHMT2 levels correlating associating strongly with tumour size, lymph node and distant metastases, stage and Gleason score." (PMID 39763034, 2025). "Euchromatic Histone Lysine Methyltransferase 2 (G9a/EHMT2; hereafter G9a) has been associated with tumor-promoting activity in several tumor types, including RMS." (PMID 37345159, 2023). "EHMT2 overexpression has been mainly attributed to transcriptional dysregulation or high copy number and has been linked to advanced tumor stage, metastasis, poor prognosis, and drug resistance." (PMID 37190128, 2023). "In lung tumorigenesis, we observe that EHMT2 loss at the time of tumor initiation leads to a significant reduction in tumor formation, as well as, tumor burden resulting in significantly increased overall survival." (PMID 35983994, 2022). "G9a encoded by EHMT2 (euchromatic histone lysine N-methyltransferase 2) is a mammalian histone methyltransferase responsible for histone H3-lysine 9 methylation (H3K9) that contributes to the epigenetic silencing of tumor suppressor genes." (PMID 35641480, 2022). "The reduced tumor growth upon EHMT2 deficiency was reversed by recombinant DKK1 or LGK974, which also inhibits Wnt signaling." (PMID 33252038, 2020). "EHMT2 is frequently overexpressed, and, in some cases, mutated, and contributes to various malignancies by enhancing cell proliferation, survival, and metastasis through its ability to silence tumor suppressor genes and facilitate oncogenic pathways." (PMID 41366520, 2026). "Since Ehmt2 knockdown inhibited tumor growth, we also asked whether the differences in NK cell infiltration were due to the differences in tumor volumes or were driven by the loss of Ehmt2 expression." (PMID 41366520, 2026). "The impaired regenerative capacity of AT2 cells observed by EHMT2 loss, together with the Wnt signaling effects impelled us to examine the outcome of EHMT2 deletion in Kras-dependent tumor initiation–an event that was previously shown to require cell fate alterations in other tissue contexts." (PMID 35983994, 2022). "This study identifies the histone methyltransferase EHMT2 as a key suppressor of NK cell-mediated anti-tumor immunity." (PMID 41366520, 2026). "We found that Ehmt2 knockdown resulted in significantly reduced tumor growth inhibition in Rag2 KO mice." (PMID 41366520, 2026). "These functions together contribute to the downstream suppressive effects of EHMT2 on NK cell anti-tumor immunity." (PMID 41366520, 2026). "As expected, Ehmt2 loss promoted NK cell infiltration as observed by an increased number of NK cells in the Ehmt2 shRNA tumor group compared to the NS shRNA-expressing tumor group (Fig. EV7C)." (PMID 41366520, 2026). "Tumor suppression by EHMT2 inhibition was NK cell-dependent, highlighting its potential as a therapeutic target." (PMID 41366520, 2026). "We found that even before tumor volumes became significantly different, the Ehmt2 shRNA tumor group showed a higher number of infiltrating NK cells compared to the NS shRNA tumor group (Fig. EV6I)." (PMID 41366520, 2026). "By suppressing AZGP1 and increasing TGF-β1, EHMT2 contributes to an immunosuppressive tumor environment." (PMID 41366520, 2026).
tumor (continued). "To further determine the importance of NK cells in Ehmt2 knockdown-mediated tumor growth inhibition in vivo, we injected Ehmt2 knockdown Panc02 cells into Rag2 knockout (Rag2 KO) mice, which lack T and B cells but have NK cells." (PMID 41366520, 2026). "We found that Ehmt2 knockdown enhanced EMT6-driven tumor clearance in syngeneic BALB/c mice, which was rescued following NK cell depletion (Fig. EV7A,B)." (PMID 41366520, 2026). "In conclusion, our study identifies EHMT2 as a cell-extrinsic driver of tumor growth that largely works via suppressing NK cell-mediated anti-tumor immunity, primarily through the repression of AZGP1 and activation of the TGF-β1." (PMID 41366520, 2026). "In immunocompetent mouse models, inhibition of EHMT2 suppressed tumor growth in an NK cell-dependent manner." (PMID 41366520, 2026). "The inhibition of EHMT2 reduces proliferation, motility, and tumor growth, effects reversible by RAC1 re-expression." (PMID 40508013, 2025). "Elevated EHMT2 expression is commonly reported in multiple human malignancies and is strongly related to tumour progression, metastasis and poor prognosis." (PMID 39763034, 2025). "EHMT2 is known to influence numerous signalling pathways, with its effects dependent on tumour progression, genetic background and interactions within the tumour microenvironment." (PMID 39763034, 2025). "DDX5 is significantly upregulated in ARMS and supports tumor cell proliferation and survival both in vitro and in vivo, partly through its interaction with the histone methyltransferase EHMT2." (PMID 40950397, 2025). "Our findings indicate that EHMT2, along with several mitotic kinases, is markedly upregulated in metastatic PCa tissues relative to primary tumours." (PMID 39763034, 2025). "Tumours in the EHMT2 knockdown group showed significant reductions in size and weight relative to the control group." (PMID 39763034, 2025). "To validate the aggravated inflammatory response in Ehmt2fl/fl animals in comparison to the Ehmt2+/+, we analyzed our spatial transcriptomics using a gene profile for the tumor inflammation signature (TIS)." (PMID 38948355, 2024). "Inhibition of EHMT2 has been shown to modulate tumor suppressor genes, drug metabolism, DNA repair, and cell survival pathways as well as to increase radiosensitivity." (PMID 37190128, 2023). "Among the genes that showed differential expression in DLBCL tumor versus normal tissues, we focused on EHMT2/G9a, a histone methyltransferase that regulates chromatin structure and gene transcription." (PMID 37627178, 2023). "Using this approach we identified BIX-01294, a molecule that inhibits histone methyltransferase EHMT2/G9A, involved in anti-tumour immune response and chemoresistance in HGSC." (PMID 37120667, 2023). "To evaluate the functional necessity of EHMT2 activity on in vivo tumor formation, we evaluated tumor formation following serial transplantation of orthotopically transplanted KP-derived primary cells harboring doxycycline (Dox)-inducible shRNAs." (PMID 35983994, 2022). "Our work implicates EHMT2 as an important mediator of Wnt signals in order to maintain tumor propagating capacity." (PMID 35983994, 2022). "To elucidate the mechanistic basis of EHMT2 in maintaining tumor self-renewal, we characterized the phenotypic impact of pharmacological inhibition of EHMT2 in tumorspheres." (PMID 35983994, 2022). "Among them, euchromatic histone-lysine N-methyltransferase 2 (EHMT2) performs mono- and dimethylation of histone H3 lysine 9 to generate heterochromatin for the repression of tumor suppressor genes." (PMID 34972816, 2022). "T-ALL displayed higher EHMT2/G9a expression compared to other tumor types, normal human thymocytes, or lymphocytes independent from the activation of known transcription factor or recurrent mutations." (PMID 35710782, 2022).
tumor (continued). "Of note, another report found reduced Wnt activity following EHMT2 perturbation, in three cell tumor cell lines; A549, H1299, and H1975 which invokes an APC2-mediated mechanism, albeit in a distinct cellular context from what we describe." (PMID 35983994, 2022). "Sorted shEhmt2-expressing cells from primary recipients showed a significant decrease in both ex vivo tumorspheres and in vivo secondary tumor formation, establishing a role for EHMT2 in maintaining TPC stemness." (PMID 35983994, 2022). "(F) Representative flow cytometry of tumor-propagating cells (TPCs) sorted after EHMT2 inhibitor (EHMT2i)- or vehicle control-treatment of primary tumorspheres and immuno-stained for AT2 markers SPC and CD74." (PMID 35983994, 2022). "Taken together, the data indicate that EHMT2 activity represses an alveolar differentiation program in murine LUAD as a means to preserve stem-like properties that enable tumor self-renewal." (PMID 35983994, 2022). "Mice harboring shEhmt2-expressing tumors eventually succumb to tumor outgrowth; however, analysis of terminal tumors revealed re-expression of Ehmt2 transcript to a level equivalent to that of control tumors." (PMID 35983994, 2022). "Similar to EZH2, EHMT2 inhibits the transcription of tumor suppressors by promoting the levels of H3K9me1/H3K9me2." (PMID 34409024, 2021). "Altogether, we consider that UNC0642 possesses anti-tumor functions on HCC mainly by targeting EHMT2." (PMID 34344448, 2021). "The dual inhibition of EZH2 and EHMT2 can induce gene transcription and inhibit tumor cell growth more effectively." (PMID 34409024, 2021). "We also carried out a xenograft assay using APC-overexpressed Hep3B and Huh1 cells to investigate the association between EHMT2 and APC in tumor growth in vivo." (PMID 34344448, 2021). "Similar to EZH2, EHMT2 inhibits the transcription of tumor suppressor genes by promoting the methylation and dimethylation of H3K9me1/3K9me2." (PMID 34409024, 2021). "In the xenograft assay, we observed that deletion of EHMT2 in Hep3B and Huh1 led to tumor growth suppression." (PMID 34344448, 2021). "Over the past decade, the anti-tumor effects of EHMT2 inhibitors have been extensively investigated by independent groups." (PMID 34344448, 2021). "c-MYC interacts with histone methyltransferase EHMT2 to repress gene transcription, and knockdown of EHMT2 results in decreased tumor volume." (PMID 33628735, 2020). "Taken together, our studies demonstrate that inhibition of EHMT2 expression or activity promotes differentiation and reduces tumor progression by regulating Wnt signaling." (PMID 33252038, 2020). "Euchromatic histone-lysine N-methyltransferase 2 (EHMT2/G9a) regulates H3K9me2 and is found overexpressed in several tumor cell lines during hypoxia." (PMID 30939818, 2019). "Our findings indicated that administering an EHMT2 inhibitor in combination with Erlotinib had a significant effect on tumor growth in preclinical models." (PMID 29374157, 2018). "Remarkably, Beclin-1 showed a completely reciprocal expression pattern compared with EHMT2 in tumor tissue." (PMID 27174920, 2016). "Histone lysine methyltransferases, such as the H3K36 methyltransferase Whsc1/Nsd2 and the H3K9 methyltransferase G9a/Ehmt2, have been shown to play critical roles in tumor invasion and metastasis formation." (PMID 23520493, 2013). "We identified specific H3K4 and H3K9 methyltransferases, such as Mll, Mll3, Setd1a, Ehmt2, Suv39h1, and Setdb1 as biomarkers of residual tumor cells persisting after chemotherapy." (PMID 23520493, 2013). "Finally, EHMT2 and TGF-β1 inhibitors reduced tumor growth, identifying EHMT2 as a promising, druggable target that suppresses NK cell-mediated anti-tumor immunity via TGF-β1-mediated autocrine and paracrine effects." (PMID 41366520, 2026). "However, the role of EHMT2 in the regulation of NK cells-mediated anti-tumor immunity has remained unexplored." (PMID 41366520, 2026).
tumor (continued). "We found that Ehmt2 knockdown enhanced EMT6-driven tumor clearance in syngeneic BALB/c mice." (PMID 41366520, 2026). "EHMT2 has been identified as a key epigenetic barrier to NK cell-driven tumor immunity." (PMID 41366520, 2026). "Furthermore, we uncovered that EHMT2 promotes colorectal tumorigenesis, revealing a novel mechanistic link between rDNA transcriptional regulation and tumor promotion." (PMID 41851073, 2026). "We found that Ehmt2 knockdown in Panc02 resulted in reduced tumor growth in C57BL/6 mice." (PMID 41366520, 2026). "We found that the inhibition of EHMT2 in tumor cells increased AZGP1, which reduced TGF-β1 levels." (PMID 41366520, 2026). "Finally, we tested pharmacological inhibition of EHMT2 or TGF-β1 as an approach to enhance anti-tumor immunity against tumor cells." (PMID 41366520, 2026). "Furthermore, NK cell depletion in these mice restored tumor growth of Panc02 tumors expressing Ehmt2 shRNAs." (PMID 41366520, 2026). "Moreover, consistent with strong tumor suppression, we noted reduced Ki-67 staining in Panc02 tumors expressing Ehmt2 compared to those expressing NS shRNA from immunocompetent syngeneic C57BL/6 mice (Fig. EV6E,F)." (PMID 41366520, 2026). "Finally, in vivo experiments using xenograft models demonstrated that DDX5 depletion results in significantly impaired tumor growth, accompanied by reduced expression of both EHMT2 and PAX3-FOXO1." (PMID 40950397, 2025). "Investigating the combined effects of EHMT2 inhibitors with AR signalling inhibitors could be valuable, potentially enhancing tumour‐cell eradication by targeting both G1/S and M‐phase transitions in CRPC." (PMID 39763034, 2025). "Notably, EHMT2‐shRNA DU145 xenograft tumours showed higher anaphases with chromosome segregation mistakes relative to control tumours." (PMID 39763034, 2025). "After 72 h, both EHMT2 inhibitors exhibited potent anti-tumour in vitro activity in all models." (PMID 37120667, 2023). "(E) Overall tumor volume in secondary recipient mice orthotopically transplanted with KP cells from primary recipients, expressing either shRNAs targeting control (shcontrol) or Ehmt2 (shEhmt2.1) (n=6) tumor volume at end of study by treatment, Mann-Whitney test, *p<0.05." (PMID 35983994, 2022). "Importantly, this AT2-like conversion was confirmed in Ehmt2-depleted tumor cells from secondary passage in vivo." (PMID 35983994, 2022). "Moreover, we also show that metastatic samples had an EHMT2/G9a expression significantly higher than that of primary and recurrent tumor samples." (PMID 35354905, 2022). "Moreover, all these observations were largely abolished by the deletion of EHMT2 from cells, suggesting UNC0642 achieves its anti-tumor effects in an EHMT2 dependent manner." (PMID 34344448, 2021). "In addition, the discovery that inhibition of EHMT2 in epithelial cells leads to reorganization of the immune landscape in the tumor microenvironment serves as the foundation for future studies focused on designing combinations with immunomodulatory agents." (PMID 34249932, 2021). "In Huh-7 and SMMC-7721 cells, HSF2 was shown to interact with euchromatic histone lysine methyl transferase 2 (EHMT2) in order to epigenetically silence the gene encoding fructose-bisphosphatase 1 (FBP1), which is a tumor suppressor and negative regulator of aerobic glycolysis." (PMID 32408596, 2020). "EHMT2 has been proposed to have oncogenic functions and its overexpression in leukemia, gastric, lung, prostate cancer, and alveolar RMS causes silencing of tumor suppressor genes through its H3K9me2 activity." (PMID 33252038, 2020). "In contrast, EHMT2 was frequently upregulated in tumor samples." (PMID 32292512, 2020). "Additionally, our study provides a rationale for therapies administered in combination with 5-Aza-Cd to effectively reprogram the transcription of silenced genes in tumor cells based on assessments of the expression levels of EHMT2 and DNMT1." (PMID 27174920, 2016).